OGFOD1 (2-oxoglutarate and iron dependent oxygenase domain containing 1)
Description:
Prolyl 3-hydroxylase that catalyzes 3-hydroxylation of 'Pro-62' of small ribosomal subunit uS12 (RPS23), thereby regulating protein translation termination efficiency. Involved in stress granule formation.
Synonyms: KIAA1612; TPA1; FLJ10826
Tractability: Small molecule: a structure with a bound ligand is known; a high-quality ligand is known. PROTAC: ubiquitination databases record sites on it; a small molecule that binds it is known.
Target class: Enzyme; Oxidoreductase
Gene: Protein-coding gene on chromosome 16 (56,451,508 to 56,479,104, forward strand). Ensembl gene ENSG00000087263.
Subcellular location: Cytoplasm (Isoform 1); Nucleus; Cytoplasm (Isoform 2)
Subcellular location (Human Protein Atlas): Nucleoplasm; Cytosol
Pathways (Reactome):
Metabolism of proteins: Protein hydroxylation
Gene Ontology:
Molecular function: peptidyl-proline 3-dioxygenase activity; peptidyl-proline dioxygenase activity; protein binding; 2-oxoglutarate-dependent dioxygenase activity; iron ion binding; L-ascorbic acid binding; oxidoreductase activity, acting on paired donors, with incorporation or reduction of molecular oxygen
Biological process: cell population proliferation; peptidyl-proline hydroxylation; protein hydroxylation; regulation of translational termination; stress granule assembly
Cellular component: cytoplasmic stress granule; cytosol; nucleoplasm; cytoplasm; nucleus
Genetic constraint (gnomAD): Loss-of-function variants: 39 observed, 50.66 expected, observed/expected ratio (o/e) 0.77, 90% interval 0.6 to 1.01. The upper end of that interval is the gene's LOEUF score, 1.01, which puts it in group 4 of 6, group 1 being the genes least tolerant of losing a copy. Missense variants: 488 observed, 550.35 expected, observed/expected ratio (o/e) 0.89, 90% interval 0.82 to 0.96. Synonymous variants: 183 observed, 196.14 expected, observed/expected ratio (o/e) 0.93, 90% interval 0.83 to 1.05.
Homologues: Orthologues: chimpanzee OGFOD1 (98% identical), macaque OGFOD1 (95% identical), dog OGFOD1 (89% identical), pig OGFOD1 (88% identical), rabbit OGFOD1 (87% identical), guinea pig OGFOD1 (86% identical), mouse Ogfod1 (83% identical), rat Ogfod1 (82% identical), tropical clawed frog ogfod1 (55% identical), zebrafish ogfod1 (52% identical), Drosophila melanogaster sud1 (28% identical), Caenorhabditis elegans C17G10.1 (26% identical).
Diseases named in the same sentence as OGFOD1 in open-access papers:
OGFOD1 is named in the same sentence as 21 diseases in open-access papers, as found by Europe PMC text mining. Sharing a sentence is not in itself a finding about the gene and the disease. The quoted sentences say what the papers report.
breast carcinoma (3 papers, 2015 to 2026). "OGFOD1 is implicated in the pathogenesis of various cancers, including lung cancer, breast cancer and colonic cancer." (PMID 42088572, 2026). "Elevated OGFOD1 levels have been reported in a variety of cancers such as chronic lymphocytic leukemia, breast cancer, and laryngeal papilloma and are associated with abnormal cell proliferation, dysregulated cell cycle, and poor prognosis." (PMID 34298635, 2021). "Thus, we propose that OGFOD1 is required for breast cancer cell proliferation and is associated with poor prognosis in breast cancer." (PMID 25909288, 2015). "Next, we performed Kaplan-Meier survival analysis to determine whether greater OGFOD1 expression was linked to the clinical prognosis of breast cancer patients." (PMID 25909288, 2015). "Recent reports have detailed a high expression level of OGFOD1 in proportion to cancer progression induced by oncogenes or microRNAs that are associated with poor prognosis in tumors, including chronic lymphocytic leukemia, breast cancer, laryngeal papilloma, and colon cancer." (PMID 34298635, 2021). "We demonstrated that OGFOD1 plays a role in enhancing the transcriptional activity of RNA polymerase II in breast cancer cells." (PMID 34298635, 2021). "Both protein and mRNA levels of OGFOD1 were highly expressed in breast cancer cells compared to epithelial cells." (PMID 34298635, 2021). "Overall, we uncovered the novel mechanism for how OGFOD1 maliciously functions in breast cancers, suggesting it as a rational cancer treatment target protein." (PMID 34298635, 2021). "Compared to breast cancer cell lines, we found that OGFOD1 aggravates cancers by enhancing RNA polymerase II transcriptional activity and it is improved by cell cycle-dependent kinases." (PMID 34298635, 2021). "Even though OGFOD1 was upregulated among breast cancer cell lines, the levels varied in each cell lines." (PMID 34298635, 2021). "When OGFOD1 levels were reduced, all of the breast cancer cell lines exhibited a remarkably impeded proliferation rate." (PMID 34298635, 2021). "To confirm the clinical significance of elevated OGFOD1 in breast cancer, we collected public mRNA microarray data from breast cancer patients and analyzed OGFOD1 expression with regard to PAM50-defined disease subtypes." (PMID 25909288, 2015). "In this study, we demonstrate that OGFOD1 knockdown in breast cancer cells inhibits cellular proliferation and triggers severe G2/M arrest." (PMID 25909288, 2015). "Based on the staining intensity of representative immunohistochemical photographs of OGFOD1 in breast cancer tissues, we performed a survival analysis." (PMID 25909288, 2015). "In conclusion, our results implicate a novel function for OGFOD1 in breast cancers: OGFOD1 stimulates cell cycle progression, and its elevation effects the proliferation of breast cancer cells." (PMID 25909288, 2015). "We also confirmed that OGFOD1 is highly expressed in breast cancer tissues by bioinformatic analysis and immunohistochemistry." (PMID 25909288, 2015). "Of 1115 human breast cancer tissues, 316 had high OGFOD1 expression (28.3%), whereas 799 expressed low levels of OGFOD1 (71.7%) (P < 0.0002)." (PMID 25909288, 2015). "In this study, we have demonstrated that OGFOD1 protein and mRNA levels are high in breast cancer patient tissues, consistent with data that OGFOD1 knockdown significantly downregulates G2/M-related genes, which are highly expressed in breast cancers." (PMID 25909288, 2015). "In this study, knockdown of OGFOD1 in MDA-MB-231 breast cancer cells significantly reduced cellular proliferation, consistent with a previous report." (PMID 25909288, 2015). "The expression of OGFOD1 protein and mRNA was significantly greater in breast cancer cell lines compared with MCF-10A cells." (PMID 25909288, 2015).
breast carcinoma (continued). "OGFOD1 was hardly detectable in normal human tissues, whereas OGFOD1 expression was high in the corresponding cancer tissues, including breast cancer, which is consistent with the overexpression of OGFOD1 mRNA in the Oncomine database." (PMID 25909288, 2015). "To determine the function of OGFOD1, we first knocked down OGFOD1 in MDA-MB-231 breast cancer cells using a lentivirally expressed shRNA system." (PMID 25909288, 2015). "OGFOD1 knockdown in MDA-MB-231 breast cancer cells significantly impeded cell proliferation and resulted in the accumulation of G1 and G2/M cells by decreasing the mRNA levels of G1/S transition- and G2/M-related transcription factors and their target genes." (PMID 25909288, 2015). "We also confirmed that OGFOD1 is highly expressed in breast cancer tissues." (PMID 25909288, 2015). "We propose that overexpression of OGFOD1 is a marker of poor prognosis in breast cancers." (PMID 25909288, 2015). "Next, we sought to figure out whether upregulated OGFOD1 affects breast cancer property." (PMID 34298635, 2021). "Here, we identified a novel function for nuclear OGFOD1 in the enhancement of RNA polymerase II transcriptional activity and how this is governed by CDK7 activity in breast cancer cells." (PMID 34298635, 2021). "In order to examine the role of OGFOD1 in breast cancer cell lines, we verified the expression level of OGFOD1 in MDA-MB-231, HCC1954, T47D, MCF7, and non-tumorigenic epithelial cell line MCF10A." (PMID 34298635, 2021). "At this stage, although there is no direct evidence that the enzymatic activity of OGFOD1 is involved in the regulation of the cell cycle, we propose that OGFOD1 is important for cell cycle progression and that its elevation leads to cellular proliferation in breast cancers." (PMID 25909288, 2015).
colon cancer (2 papers, 2021 to 2026). "Myc, a representative oncogene, can also induce OGFOD1 expression via the aryl hydrocarbon receptor in colon cancer." (PMID 34298635, 2021).
breast tumor (1 paper, 2015). "We confirmed that these molecular events are consistent with the high expression of OGFOD1 in human breast tumor tissues by immunohistochemistry and bioinformatic analysis of public microarray data." (PMID 25909288, 2015). "To determine the clinical significance of OGFOD1 in breast tumor patients, we analyzed the survival rates of patients by OGFOD1 expression in several normal versus tumor tissues (Oncomine database)." (PMID 25909288, 2015). "Low OGFOD1 expression (scored as 0 and 1) did not affect the survival of breast tumor patients, whereas high expression (scored as 2 and 3) correlated significantly with poor survival (P < 0.05)." (PMID 25909288, 2015).
cardiac hypertrophy (1 paper, 2024). "OGFOD1 deletion leads to protection in cardiac ischemia-reperfusion injury and cardiac hypertrophy, which are two cardiac events that can lead to heart failure." (PMID 38843265, 2024).
diabetes (1 paper, 2024). "Considering the remarkable correlation between heart disease and diabetes, the cardioprotection observed in OGFOD1-knockout mice led us to challenge these knockouts with high-fat diet." (PMID 38843265, 2024).
glioblastoma (1 paper, 2022). The most malignant astrocytic tumor (WHO grade IV). "Although OGFOD1, C1RL, CD81, and ITPKC play pivotal roles in several cancers, their involvement in glioblastoma remains undocumented." (PMID 35936722, 2022).
Glucose intolerance (1 paper, 2024). Glucose intolerance (GI) can be defined as dysglycemia that comprises both prediabetes and diabetes. "Wildtype mice fed a high-fat diet developed diet-induced obesity, insulin resistance, and glucose intolerance, but OGFOD1 knockout mice fed this same diet were resistant to diet-induced obesity and insulin resistance." (PMID 38843265, 2024).
ischemic stroke (1 paper, 2024). A stroke disorder caused by obstruction of blood flow to the brain, due to thrombotic (local blood clot formation) or embolic (due to a blood clot or other material traveling from another site) event. "The inhibition of OGFOD1 is a novel therapy for ischemic stroke." (PMID 38454480, 2024).
cancer (7 papers, 2015 to 2026). A tumor composed of atypical neoplastic, often pleomorphic cells that invade other tissues. "Collectively, in MDA-MB-231 cells, OGFOD1 knockout decreased several metastasis-associated genes, resulting in the inhibition of cancer development." (PMID 34298635, 2021). "Here, we showed that loss of OGFOD1 reduced RNA polymerase II transcriptional activity in cancer, leading to a reduction in metastatic gene expression and tumor growth retardation, and that this effect was related to the nuclear position of OGFOD1." (PMID 34298635, 2021). "We adopted a proximity-dependent labeling approach using an engineered ascorbate peroxidase (APEX2) system to determine how OGFOD1 affects cancer proliferation." (PMID 34298635, 2021). "Taken together, these results indicate that the nuclear localization of OGFOD1 contributes to cancer development through RNA polymerase II." (PMID 34298635, 2021). "Although several studies have attempted to examine the physiological role of OGFOD1, the exact action of OGFOD1 in cancer remains undescribed." (PMID 34298635, 2021). "Since we newly discovered the connection between OGFOD1 and RNA polymerase II and it is considered as a critical process of regulating cancer properties, we attempted to confirm their relation." (PMID 34298635, 2021). "2-oxoglutarate and iron-dependent oxygenase domain-containing protein 1 (OGFOD1) expression is upregulated in a variety of cancers and has been related to poor prognosis." (PMID 34298635, 2021). "Urokinase-type plasminogen activator receptor, uPAR, an OGFOD1 target gene, recruits uPA on the cell membrane to trigger extracellular matrix degradation, which is a frequently upregulated pathway in cancers." (PMID 34298635, 2021). "Despite the rational evidence between OGFOD1 and cancer, the exact relationship is poorly understood." (PMID 34298635, 2021). "In addition, CDK7/9 phosphorylate serine 256 of OGFOD1, which promotes its driving ability in cancer both in vitro and in vivo." (PMID 34298635, 2021). "OGFOD1 is increased in many cancers and regulates both transcription and translation; therefore, there may be a role for OGFOD1 in cancer development." (PMID 34298635, 2021). "Similarly, OGFOD1 KO- and S256A-OGFOD1-expressing cells significantly reduced migration and invasion, which are distinct characters of cancer." (PMID 34298635, 2021). "However, despite a significant function being indicated in cancer progression, the precise mechanism of how OGFOD1 exacerbates cancer remains elusive." (PMID 34298635, 2021). "The expression of OGFOD1 was significantly higher in cancer tissues versus normal tissues." (PMID 25909288, 2015). "Then, we studied whether OGFOD1 is highly expressed in various types of cancers by immunohistochemistry using tissue array." (PMID 25909288, 2015). "For example, the methylation regions located in ACAA2, NUSAP1, OGFOD1, PSMD5, SNRNP40, USP37 and XRCC6 are shared by five cancers (i.e., BRCA, CESC, COAD, KIRP and SARC)." (PMID 34464378, 2021). "However, despite this significance to cancer progression, the precise oncogenic mechanism of OGFOD1 is not understood." (PMID 34298635, 2021).
tumor (2 papers, 2015 to 2021). "Here, we observed that the elimination of OGFOD1 causes a reduction in tumor improvement." (PMID 34298635, 2021). "Consequently, we identified that OGFOD1 is associated with tumor progress through enhancing RNA polymerase II-dependent transcription in MDA-MB-231." (PMID 34298635, 2021). "Xenograft tumor experiments were assigned to four groups: control, OGFOD1 KO, KO + WT, and KO + S256A." (PMID 34298635, 2021). "With OGFOD1 deletion, tumor growth was remarkably inhibited in agreement with what we observed in vitro." (PMID 34298635, 2021). "OGFOD1 also has an oncogenic property in these contexts and phosphorylation of OGFOD1 by CDKs stimulates tumor formation; therefore, we suggest that there is an overlapping role in tumorigenesis." (PMID 34298635, 2021). "In conclusion, we have demonstrated that OGFOD1 stimulates cellular proliferation by influencing cell cycle progression and that highly elevated levels of OGFOD1 promote cell cycle progression and eventually trigger tumor formation in breast cells." (PMID 25909288, 2015). "The elimination of OGFOD1 resulted in decreased tumor development." (PMID 34298635, 2021). "Notably, the restoration of wild-type OGFOD1 expression rescued tumor growth; however, the expression of the S256A OGFOD1 abated the oncogenic effect." (PMID 34298635, 2021). "This indicates that reduced uPAR function following OGFOD1 knockout prevented tumor progression." (PMID 34298635, 2021). "Consequently, OGFOD1 helps promote tumor growth by enhancing RNA polymerase II, whereas simultaneous phosphorylation of OGFOD1 by CDK enzymes is essential in stimulating RNA polymerase II-mediated transcription both in vitro and in vivo, and expression of target genes." (PMID 34298635, 2021). "Additionally, cell cycle-dependent kinase 7 and cell cycle-dependent kinase 9, critical enzymes for activating RNA polymerase II, phosphorylated serine 256 of OGFOD1, whereas a non-phosphorylated mutant OGFOD1 failed to enhance transcriptional activation and tumor growth." (PMID 34298635, 2021). "Indeed, non-phosphorylated substitution hampered OGFOD1 oncogenic characteristics, including rapid proliferation, invasion, and metastasis, implying that CDK-mediated phosphorylation of OGFOD1, as well as RNA polymerase II, endows aggressive tumor proliferation." (PMID 34298635, 2021).
OGFOD1 also shares sentences with these, for which no sentence is quoted: laryngeal papilloma (2 papers); acute myeloid leukemia (1); chronic lymphocytic leukemia (1); COVID-19 (1); heart disease (1); heart failure (1); infection (1); Insulin resistance (1); lung carcinoma (1); Obesity (1); pyometra (1).